CDK4 (cyclin dependent kinase 4)
Diseases named in the same sentence as CDK4 in open-access papers (continued):
Sharing a sentence is not in itself a finding about the gene and the disease.
breast cancer (continued). "Further evaluation of the estradiol-challenge test with FFNP-PET in predicting CDK4/6 inhibitor efficacy in ER+ breast cancer is warranted." (PMID 33531464, 2021). "The mechanisms include: CDK4/6 inhibitors reduce the proliferation of immunosuppressive T-reg cells, increase tumor antigen presentation in breast cancer cells, stimulate type III IFN production, and promote the infiltration and activation of T-cells." (PMID 34026622, 2021). "Overall, since breast cancer patients resistant to CDK4/6 inhibitors can gain resistance due to an FGFR1 amplification, the same therapeutic effect of FGFR1 inhibition will likely be seen if a future study focuses on this specific population." (PMID 34830174, 2021). "To clarify this, we compared antitumor activity of six chemotherapeutic agents commonly used in clinics among breast cancer cells sensitive or resistant to CDK4/6 inhibitors in this study." (PMID 32860163, 2021). "The resistant cells also formed more autophagosomes, further highlighting that ER+ breast cancer cells upregulate autophagy to cope with pharmacological CDK4/6 inhibition." (PMID 34830174, 2021). "Since antiestrogens are combined with CDK4/6 inhibitors in the clinic to treat advanced ER+ breast cancer, we sought to determine the effect of these drugs on cell proliferation in drug sensitive and resistant cells." (PMID 34277427, 2021). "Combinations with BH3 mimetics such as venetoclax that target the Bcl-2 family of apoptosis inhibitors offer a potential rational combination in the setting of CDK4/6i resistant ER+ breast cancer." (PMID 34804982, 2021). "Here, we present our experience regarding joint symptoms in breast cancer patients treated with CDK4/6 inhibitors." (PMID 34198899, 2021). "In the case of CDK4/6 these are the D type cyclins which are transcriptional targets of ERα and frequently upregulated in ER+ breast cancer, providing the rationale for targeting this axis in ER+ breast cancer." (PMID 34804982, 2021). "Palbociclib is the first Food and Drug Administration (FDA)-approved CDK4/6 inhibitor with the capacity to improve progression-free survival of breast cancer patients in combination with fulvestrant or letrozole." (PMID 34948218, 2021). "In vitro experiments treating MCF7 and T47D cells with palbociclib display the ease with which breast cancer cells can become resistant to CDK4/6 inhibition." (PMID 34830174, 2021). "Specifically, CDK4/6 oncogenic activation has been reported in luminal breast cancer, constituting one of the main tumorigenic drivers." (PMID 34646365, 2021). "This case report presents a real-life case of cyclin-dependent kinase 4/6 inhibitors use in a patient initially considered to have stage IV luminal HER2-negative breast cancer with liver metastasis." (PMID 34458177, 2021). "This study assesses the use and efficacy of everolimus exemestane in patients with metastatic HR+ HER2− breast cancer previously treated with endocrine therapy (ET) or endocrine therapy + CDK4/6i." (PMID 33514405, 2021). "We report sensitivity to numerous clinically approved inhibitors, including CDK4/6 inhibitor ribociclib, which is a standard-of-care therapy in the treatment of metastatic ERα-positive breast cancer and currently under evaluation in the neoadjuvant setting." (PMID 34944934, 2021). "Palbociclib has been actively applied in multiple preclinical models and was approved for targeting CDK4/6 as anticancer therapy for breast cancer; however, acquired resistance occurs in almost all cases." (PMID 33477856, 2021). "In this prospective study, we observed proof‐of‐concept that longitudinal ctDNA z‐score trajectories harbor important dynamic information on the development of disease progression in HR+HER2− breast cancer patients undergoing CDK4/6 inhibitor treatment." (PMID 33264486, 2021).
breast cancer (continued). "Estrogen-mediated hyperactivity of the CCND–CDK4/6 axis is a central feature of HR-positive breast cancer, and the tumors usually retain a functional Rb, which can be targeted by CDK4/6 inhibitors." (PMID 33845905, 2021). "Palbociclib, a highly selective CDK4/6 inhibitor, which blocks the replication cycle and proliferation of tumor cells, is a promising anticancer drug for breast cancer patients." (PMID 33767584, 2021). "To investigate the mechanisms of action responsible for resistance, we developed breast cancer cells resistant to CDK4/6 inhibitors, and analyzed their biological characteristics and sensitivity to different anticancer agents." (PMID 32860163, 2021). "The study of CDK4/6 inhibitors was mainly focused on oncology, including breast cancer, glioblastoma, and myeloma 25-29." (PMID 33995631, 2021). "Though several trials are investigating the combination of CDK4/6 inhibition and anti-PD-1/PD-L1 therapy in advanced breast cancer (NCT02778685, NCT04360941), such an approach has to our knowledge not been attempted in NSCLC." (PMID 34625620, 2021). "Inhibition of either SMYD2 or CDK4/6 would restore the ciliation of cystic renal epithelial cells and breast cancer cells." (PMID 34359832, 2021). "Since CDK4/6 is known to promote cancer progression in many entities, palbociclib has been approved for therapy of breast cancer." (PMID 34722291, 2021). "Here, the authors report that inhibition of CK1ε can prevent acquisition of CDK4/6i resistance, potentiating the therapeutic efficacy of CDK4/6i in human breast cancer." (PMID 34508104, 2021). "CDK4/6 inhibitors in combination with endocrine therapy has shown efficacy in ER + breast cancer patients but resistance can occur." (PMID 34433817, 2021). "Nevertheless, BCSCs, as a main source of cancer relapse, remained largely intact in vitro upon CDK4/6i, HR antagonists, and autophagy inhibition in ER+ breast cancer cells." (PMID 34207792, 2021). "Overall, 2457 patients with diverse solid tumors that underwent clinical-grade, next-generation sequencing (182–465 genes) and therapy outcome of (non–breast cancer) patients treated with matched CDK4/6 inhibitors were analyzed." (PMID 33427211, 2021). "As mentioned, the critical role of CDK4 in the pathogenesis of PC, and the recent success of CDK4/6i in breast cancer, makes CDK4-inhibition a promising target for future therapeutics in the treatment of PC." (PMID 34828525, 2021). "With the increase in the number of clinical trials, studies on CDK4/6 inhibitors have also expanded from breast cancer to other types of human cancer 25-29." (PMID 33995631, 2021). "IGF2-targeting and MDM2-targeting drugs have been in clinical trials for other tumor types, and CDK4/6 inhibitors are already approved for patients with breast cancer." (PMID 34680217, 2021). "By themselves, the CDK4/6is have some efficacy in breast cancer, but they are most effective when used in combination with estrogen receptor inhibitors and aromatase inhibitors." (PMID 34138895, 2021). "More specifically, in breast cancer, administration of CDK4/6 inhibitors is actively being explored alone or in combination with endocrine therapy or immunotherapy agents (NCT03425838, NCT03285412, NCT03294694, NCT04318223)." (PMID 33741974, 2021). "In support of the critical roles they played in cell cycle progression, loss of RB1 and upregulation of CDK6 rank on the top hits in driving breast cancer cell evasion from CDK4/6i treatment induced cell cycle blockade." (PMID 34508104, 2021).
breast cancer (continued). "Currently, inhibitors targeting CDK4/6 activity (abemaciclib, palbociclib, and ribociclib) have been approved for clinical use in breast cancer patients." (PMID 34065619, 2021). "Altogether, our bioinformatics analysis of clinical information from breast cancer patients strongly suggested that CDK2 and CDK4 are biomarkers of tumor progression, metastasis, and prognostic and therapy responses in breast cancer." (PMID 34421361, 2021). "CDK4 is such a type of gene that almost involves in the development of many types of cancer including melanoma, breast cancer and lung cancer." (PMID 34735543, 2021). "Compared to tamoxifen, which is typically prescribed for pre-menopausal breast cancer patients, fulvestrant and AIs are mainly reserved for post-menopausal cases alone or in combination with other endocrine or targeted agents such as CDK4/6 inhibitors." (PMID 33741974, 2021). "Another study suggested modulation of MYC via activated cyclin E-CDK2 as a resistance mechanism in CDK4/6i-resistant breast cancer cell models." (PMID 34771560, 2021). "For instance, while KRAS mutation is very frequent in CRC (about 40% of the cases), it is much less frequent in breast cancer and, in particular, in ER positive breast cancers (less than 1%), the tumor subtype in which CDK4/6i are more active." (PMID 34654798, 2021). "In conclusion, these results provide intriguing cellular evidence pointing to CK1ε an attractive target for preventing or overcoming CDK4/6i resistance in breast cancer cells." (PMID 34508104, 2021). "Our findings support the clinical development of triple combinations with fulvestrant, CDK4/6i, and AKTi in pre-treated ER+ advanced breast cancer, particularly in tumors exhibiting high levels of p-AKT, to improve patient survival." (PMID 34433817, 2021). "Conversely, Cdk4 and Cyclin D1 are frequently overexpressed in cancer, with CCND1 amplification present in 20% of breast cancers and CDK4 amplified in 18% of glioblastomas." (PMID 33806417, 2021). "Increased level of p21 has been reported as a biomarker predicting the sensitivity of CDK4/6 inhibitor in estrogen receptor (ER)+ breast cancer." (PMID 34761877, 2021). "Cyclin-dependent kinase 4/6 (CDK4/6) inhibitors for breast cancer treatment have been approved for use in clinical cancer therapeutics." (PMID 34490348, 2021). "CDK4/6 inhibitors have been established in the treatment of hormone receptor-positive (HR) breast cancer." (PMID 33530456, 2021). "There are three FDA-approved inhibitors of CDK4/6 for use in patients with ER+ breast cancer: palbociclib, ribociclib, and abemaciclib." (PMID 34830174, 2021). "All three FDA-approved inhibitors of CDK4/6 are now in clinical trials in combination with ICIs to treat cancers, such as breast cancer, HNSCC, NSCLC, and liver cancer." (PMID 34026622, 2021). "Cyclin-dependent kinase 4/6 (CDK4/6) inhibitors have become a mainstay of treatment for patients with advanced hormone receptor-positive (HR) breast cancer." (PMID 34439268, 2021). "In another study, the CDK4/6i trilaciclib was used in combination with chemotherapy in breast cancer patients with metastatic triple negative disease, in order to reduce dose-limiting hematological and myeloid-toxicities of chemotherapy." (PMID 34204543, 2021). "The addition of CDK4/6i to endocrine therapy in breast cancer patients has led to significant improvement of progression-free survival." (PMID 34654798, 2021). "Our differential expression analysis of CDK2 and CDK4 expression profiles revealed that both CDK2 and CDK4 are overexpressed in breast cancer tumors compared to adjacent normal tissues." (PMID 34421361, 2021). "First, we evaluated MCM3 expression by Western blotting after treating ER+ breast cancer cells with CDK4/6i alone and in combination with endocrine therapy." (PMID 33398005, 2021). "CDK4/6 inhibitors (CDK4/6i) combined with endocrine therapy have shown impressive efficacy in estrogen receptor-positive advanced breast cancer." (PMID 34433817, 2021).
breast cancer (continued). "Accordingly, pharmacological inhibition of Cdk4 and Cdk6 prevented tumor development in mouse models of breast cancer, sustained by cyclin D1, and leukemia, sustained by cyclin D3." (PMID 34204543, 2021). "Altogether, these results demonstrate that RB1 and CDK6 play a pivotal role in determining the cellular sensitivity of breast cancer cells to CDK4/6i." (PMID 34508104, 2021). "Altogether, these data suggest that E2F expression can inhibit a therapeutic response to CDK4/6 inhibition in ER+ breast cancers." (PMID 34830174, 2021). "Together, these cell proliferation studies suggest that AZD1775 is effective as a monotherapy for inhibiting cell growth in endocrine resistant and CDK4/6 inhibitor cross-resistant breast cancer cells." (PMID 34277427, 2021). "To elucidate the mechanisms of action responsible for CDK4/6 inhibitor resistance and to explore optimal treatment strategies against such resistant breast cancers, we conducted this preclinical study." (PMID 32860163, 2021). ", looked at the efficacy of alpelisib, a PI3K inhibitor, with fulvestrant in HR+/HER2-, PIK3CA-mutant advanced breast cancer after patients had previously progressed on a CDK4/6 inhibitor and aromatase inhibitor." (PMID 34830174, 2021). "Recently, CDK4/6 inhibitors have emerged as a new therapeutic approach in hormone receptor (HR)-positive breast cancer." (PMID 34198899, 2021). "Here, we investigate the molecular events driving acquisition of CDK4/6i resistance in breast cancer cells by using CRISPR/Cas9-mediated genetic screen." (PMID 34508104, 2021). "The preclinical data presented in this study provides a rationale for using WEE1 inhibitors as a promising novel therapy for endocrine resistant and CDK4/6 inhibitor resistant breast cancer." (PMID 34277427, 2021). "As breast cancer biopsies were sequenced, it became apparent that a significant proportion of patient samples exhibited dysregulation of the CDK4/cyclin D1/Rb interaction with overexpression/amplification of cyclin D1 (CCND1) and alterations in p16." (PMID 34771508, 2021). "In breast cancer cells, treatment with Palbociclib, a CDK4/6 inhibitor, upregulates mechanistic target of rapamycin (mTOR) whilst promoting G0/G1 cell cycle arrest." (PMID 33124043, 2021). "There are many more aspects about them that need to be further evaluated in the clinic to allow CDK4/6 inhibitors to reach their full potential in breast cancer treatment." (PMID 34830174, 2021). "This study provided strong evidence that this CDK4/6 inhibitor significantly aids in prolonging remission in patients with ER+ breast cancer." (PMID 34830174, 2021). "The trial is planned for patients with breast cancer who have progressed on CDK4/6 inhibitor therapy and for patients with other solid tumors that are Rb-deficient." (PMID 34686682, 2021). "On the other hand, several lines of evidence have shown that increased CDK6 protein levels conferred breast cancer cells with resistance to CDK4/6i treatment." (PMID 34508104, 2021). "Palbociclib is the first in class CDK4/6 inhibitor approved for use in patients with advanced ER+/HER2-breast cancer." (PMID 34736090, 2021). "O’Brien at al. used a reverse phase protein array in both in vitro and in vivo models of CDK4/6-resistant ER+ breast cancer to identify what pathways are still active in resistant tumors." (PMID 34830174, 2021). "Rb and cyclin E status have the potential to be used as determining factors in the response of ER+ breast cancer patients to CDK4/6 inhibitors." (PMID 34830174, 2021). "Upregulation of CDK4/6—RB pathway is common in breast cancer, especially in luminal subtypes, where cyclin D1 amplification is identified in 58% of luminal B and 29% of luminal A cancers and CDK4 amplification in 25% and 14%, respectively." (PMID 33530456, 2021). "On average, patients had been diagnosed with breast cancer 4 years earlier (SD = 6) and were taking a CDK4/6 inhibitor for 15 months (SD = 10)." (PMID 34165265, 2021).
breast cancer (continued). "Recently, we found that co-targeting CDK2, CDK6, and ER signaling inhibits the growth of ER+/HER2− breast cancer cells resistant to combined CDK4/6i and ET, supporting the use of this triple combination as a novel therapeutic strategy." (PMID 34771560, 2021). "Currently, the standard-of-care for metastatic HR+ breast cancer is the combination of either an aromatase inhibitor or fulvestrant with a CDK4/6 inhibitor, both in the first and second line." (PMID 33579347, 2021). "Among these, the mechanism by which CDK4 contributes to breast cancer progression has been thoroughly studied, and CDK4 inhibition has been applied to a wide range of human cancers." (PMID 33452764, 2021). "Like dual inhibition of estrogen and mTOR or CDK4/6 in recurrent/metastatic ER-α/PgR-positive breast cancer, the possibility of dual inhibition of androgen and mTOR or CDK4/6 is now attracting interest in TNBC." (PMID 34070471, 2021). "Overall, this study strongly supports the use of combining CDK4/6 inhibitors and antiestrogens with mTOR inhibitors to delay the onset of ER+ breast cancer resistance." (PMID 34830174, 2021). "The addition of CDK4/6 inhibitors to endocrine therapy has resulted in a significant improvement in progression-free survival (PFS) for this subtype of breast cancer." (PMID 33686962, 2021). "We show sensitivity to various clinically approved inhibitors, including CDK4/6 inhibitor ribociclib, which is a standard-of-care therapy in the treatment of metastatic ERα-positive breast cancer and currently under evaluation in the neoadjuvant setting." (PMID 34944934, 2021). "To evaluate the clinical relevance of CDK2 and CDK4 in breast cancer, we analyzed CDK2- and CDK4-related clinical information of breast cancer patients from TCGA pan-cancer database." (PMID 34421361, 2021). "Remarkably, the dependency of CDK4/6 in not limited to breast cancer alone, but to a wide range of entities like hepatocellular carcinoma, bronchial carcinoma, and head and neck squamous cell carcinoma." (PMID 34722291, 2021). "Physicians frequently prescribe cytotoxic chemotherapeutic agents to patients with advanced breast cancer resistant to CDK4/6 inhibitors." (PMID 32860163, 2021). "In contrast to previous studies using the CDK4/6 inhibitor Abemaciclib in a breast cancer model as well as in CT-26 tumor-bearing mice, we did not observe a selective decrease in the frequency of Tregs within CD4+ T cells." (PMID 34248938, 2021). "We evaluated the expression of MCM3 and AURKA by immunohistochemistry in metastatic lesions from ER+ advanced breast cancer patients treated with combined CDK4/6i and endocrine therapy (n = 86)." (PMID 33398005, 2021). "In hormone receptor positive (HR+)/HER2-negative advanced breast cancer (BC), CDK4/6i plus ET have remarkably improved survival outcomes and are now considered a standard treatment for most patients." (PMID 33536433, 2021). "In breast cancer patients, inhibition of cyclin-dependent kinases 4 and 6 (CDK4/6), which are fundamental drivers of cell cycle progression downstream of oncogenic signaling pathways, induces significant anti-tumor immune responses." (PMID 33807608, 2021). "Loss of FAT1 was also associated with poor outcome on CDK4/6i therapy, although inactivating mutations in FAT1 are rare in advanced ER+ breast cancer." (PMID 32940689, 2021). "As CDK4-targeted therapy, CDK4/6 inhibitors (e.g., abemaciclib, palbociclib, ribociclib) are currently widely used for the treatment of breast cancer, and their therapeutic value in this disease context has attracted significant attention." (PMID 34395284, 2021). "CDK4/6i has demonstrated impressive efficacy in combination with an aromatase inhibitor or fulvestrant in ER+ advanced breast cancer." (PMID 34433817, 2021). "This suggests that altered cell cycle machineries, such as the increased expression of CDK6, plays a role in the acquisition of resistance to CDK4/6 inhibitors in some breast cancers." (PMID 32860163, 2021).